GLI1 (GLI family zinc finger 1)
Diseases named in the same sentence as GLI1 in open-access papers (continued):
Sharing a sentence is not in itself a finding about the gene and the disease.
tumor (continued). "Increased levels of GLI1 protein might remain undetected when merely relying on transcriptomic profiling tools: this is especially true for cell or tumor types with activated EGFR signaling." (PMID 23762360, 2013). "Moreover, down-regulation of GLI1 or inhibition of NRP2 in SUM1315 NRP2high cells significantly decreased tumour initiation." (PMID 23436775, 2013). "Furthermore, GANT-61 inhibits PCSC-containing tumor growth, which is associated with upregulation of TRAIL-R1/DR4 and TRAIL-R2/DR5 expression and downregulation of Gli-1, Gli-2, Bcl-2, and ZEB1 expression in tumor samples obtained from nude mouse xenografts." (PMID 24325450, 2013). "Moreover, the hedgehog/GLI1 pathway contributes to the function of tumour-initiating cells in other cancer types." (PMID 23436775, 2013). "Furthermore, in tumor cells irradiated with doses higher than 6 Gy, Shh and Gli1 protein levels were reduced with the increment of irradiation dose." (PMID 23762282, 2013). "The involvement of FAK in regulating BMI-1 expression does not exclude other contributions of this kinase to the function of TICs, although its ability to induce GLI1 and, consequently, BMI-1, provides an important mechanism for its involvement in tumour formation." (PMID 23436775, 2013). "The tumor with a PTCH1 R571W mutation did not have elevated GLI1 expression, suggesting that this mutation was a passenger rather than a driver." (PMID 24368541, 2013). "Using quantitative real-time PCR (qRT-PCR), significant downregulation of the wild-type Ptch1 transcript and upregulation of the Shh target genes Gli1 and N-myc were generally observed in the tumor samples, indicating all examined MBs to be of the same Hh-dependent molecular subtype." (PMID 22438824, 2012). "In conclusion, our study suggests that the Hh pathway has a role in the pathogenesis of papillary serous ovarian cancer that may be mediated by both stromal and intra-tumor Gli1 levels." (PMID 22140510, 2011). "However, prolonged (21 days) IPI-926 treatment resulted in significant decreases in both stromal and tumor Gli1 expression." (PMID 22140510, 2011). "However, a correlation between growth inhibition and GLI1 mRNA levels were apparent at a dose of 10 μM MS-0022 across all four tumor cell lines." (PMID 21698280, 2011). "Similarly, most of the primary tumor samples showed high levels of PAX6 expression compared to GLI1 in the same samples." (PMID 21059263, 2010). "The ratio of GLI1-FL/GLI1-ΔN in seven tumor samples was higher than in paired controls." (PMID 21082031, 2010). "In several tumor cell lines, GLI1∆N expression was generally lower than wild-type GLI1." (PMID 21119888, 2010). "The discovery of tGLI1 is, thus, highly significant and is likely to open up novel concepts of the role of GLI1 in tumor biology and may provide the basis for novel treatment strategies." (PMID 21119888, 2010). "However regression analysis including the remaining pT stages (pT2 vs pT3 and pT3 vs pT4), pN status (pN0 vs pN1-3) and tumour grade (G0 vs G1-3) failed significance as independent prognostic indicators of GLI1 overexpression." (PMID 19706168, 2009). "GLI1 inhibition affects tumor cell line phenotype whether shRNA or endogenous or pharmacologic inhibitors are employed." (PMID 19859563, 2009). "Interestingly, we also found a significant positive correlation between increased nuclear GLI1 expression and aggressive tumour characteristics (i.e. tumour stage and lymph node status)." (PMID 19706168, 2009). "Moreover, evaluating combinatorial strategies that integrate GLI1 inhibition with immune checkpoint blockade or that selectively impair self-renewing tumor populations may represent a rational next step in pRCC therapy development." (PMID 41540036, 2026).
tumor (continued). "Furthermore, GLI1 facilitates tumor aggressiveness by orchestrating the tumor microenvironment (TME); it drives angiogenesis through the direct transcriptional upregulation of vascular endothelial growth factor (VEGFA) and Angiopoietin-2 (ANGPT2), essential for the hyper-vascularized nature of GBM." (PMID 41596413, 2026). "Notably, the findings reveal a connection between Smo and regulating Gli1 and PD-L1 expression, which may pave the way for developing novel anti-tumor drugs targeting these pathways." (PMID 41162883, 2025). "Based on the tumor size and anatomic location, the clinical presentations of GLI1-rearranged enteric tumors may vary, ranging from being asymptomatic and incidentally detected to abdominal pain, alterations in bowel habits, and delayed gastric emptying secondary to mass effect." (PMID 39851545, 2025). "Therefore, strategies that directly inhibit Gli1 or modulate its regulators, such as histone deacetylases or non-canonical kinases, may represent a more effective approach for sustained tumor suppression." (PMID 41439992, 2025). "Also, in the group 3 subtype, MYC as a transcription factor could regulate GLI1 expression, leading to tumor growth and relapse." (PMID 40785845, 2025). "In addition to its role in tumor growth, GLI1 contributes to treatment resistance." (PMID 40628732, 2025). "Similarly, neoplasms with GLI1 amplification and coamplification of MDM2/CDK4 could benefit from MDM2/CDK4 inhibitors." (PMID 38275873, 2024). "In addition, suppressing the Gli1-bFGF axis obviously reduced tumor angiogenesis and growth." (PMID 38493151, 2024). "Blockade of the Shh/Gli1 signaling pathway significantly suppresses tumor angiogenesis However, the role of Gli1 in mediating the crosstalk between NSCLC cells and blood vascular cells and whether this crosstalk is involved in tumor angiogenesis are still unclear." (PMID 38493151, 2024). "Similarly, significant variations in GLI1 expression were noted between T1 and T2 (p = 1.4e-05), T1 and T4 (p = 0.0015), T2 and T3 (p = 0.00046), as well as T3 and T4 (p = 0.0023) within the T stage of the tumor." (PMID 39483334, 2024). "Moreover, pharmacological inhibition of Gli1 obviously suppressed tumor angiogenesis." (PMID 38493151, 2024). "Gli1 displays a genomic association with LPS tumor initiation; however, it is not the only transcriptional activator of the Hedgehog pathway and can often display both overlapping and distinct transcriptional targets with that of Gli2, the other primary Hedgehog transcriptional activator." (PMID 37444470, 2023). "Additionally, tumors with Gli1 overexpression grew faster, whereas tumor growth was inhibited after circ-siRNA treatment.We subsequently detected Gli1 and has-circ-0011536 expression in tumors by PCR, and found that the expression of Gli1 and circ were consistent with the regulatory expectations." (PMID 38041128, 2023). "However, we observed a significant increase in Gli2 expression in DDLPS tumors compared to WDLPS tumors, leading us to hypothesize that Gli2 may play a greater functional role in tumor dedifferentiation compared to Gli1." (PMID 37444470, 2023). "We observed whether co‐inhibition of FAK and Gli1 could inhibit CCL22‐mediated tumor malignancy." (PMID 37846367, 2023). "Moreover, recent single cell transcriptomes of 21 PitNETs compared to 3 normal pituitary glands show that the SOX2+ stem-like cell compartment of PitNETs (tumor stem cells) is enriched for the expression of genes involved in HH signaling and expresses higher GLI1 and GLI2 levels." (PMID 37476499, 2023). "Furthermore, GLI1 knockdown in gefitinib-resistant PC9 cells significantly suppressed tumor growth while promoting tumor cell apoptosis, suggesting that depletion of GLI1 increases the sensitivity of chemoresistant tumors to gefitinib, possibly via EMT reversion." (PMID 35154464, 2022).
tumor (continued). "For example, the overexpression of Gli1, a key protein in the Hh pathway, is considered as a symbol of Hh pathway activation and is able to activate oncogene target genes such as Cyclin-D1, Myc, Bcl-2, Ang1/2, Snai1, Nanog, and Sox2 to promote carcinogenesis and tumour development." (PMID 36358596, 2022). "Therefore, Gli1 expression would not only suggest tumor identity, but also vismodegib resistance." (PMID 36455049, 2022). "Therefore, it may present an opportunity to develop novel therapeutic targets for tumor conditions with aberrant expression of GLI1." (PMID 33637972, 2021). "Our data also suggest that Rack1 is not only essential for GNPs proliferation and migration at postnatal cerebellar developmental stage, which may also play an important role in enhancing SHH‐type MB tumor formation by positively regulating the expression and function of Gli1 and HDAC2." (PMID 34480519, 2021). "Moreover, in the phase-I EDALINE study, tumor specimens of high responders to docetaxel were cotreated with sonidegib and characterized by elevated Hh ligand expression, GLI1 expression, ECM remodeling, FAK signaling, phosphor-FGFR (receptor of FGF-5), and ALDH1 (CSC marker)-positive cells." (PMID 34572373, 2021). "We observed that patients with high-GLI1 expression had lower levels of Mucin-2 expression than those with low-GLI1 expression, and by combining these data, a significant negative correlation between elevated expression of GLI1 and decreased expression of Mucin-2 in tumour tissues was found." (PMID 32814764, 2020). "We speculate that during treatment, there is a drop in levels of GLI1, as an end product of the Hh pathway, unless the tumour successfully maintains excessive activity of the Hh pathway via bypass pathways or adjunctive mutations that the treatment cannot overcome." (PMID 31988301, 2020). "Furthermore, GLI1 levels appeared to vary depending on the degree of tumor cell differentiation." (PMID 32913560, 2020). "Notably, GLI1/2 expression was more of a prognostic factor for TGF-β and EMT-related genes than for HH-related genes, which might suggest that GLI1/2 regulate tumor formation by regulating TGF-β-related gene expression rather than HH-induced gene expression." (PMID 32245491, 2020). "However, its effect on tumor angiogenesis and Shh/Gli1 signaling pathway are still unclear." (PMID 32286274, 2020). "Additionally, the observation that GLI1ΔN is downregulated in tumor tissues compared to normal tissues suggests that alternative splicing of GLI1 mRNA may function as a regulatory sink to control pathway activity." (PMID 32957513, 2020). "However, GLI1 showed elevated expression in tumour tissue compared with matched normal tissue." (PMID 32814764, 2020). "Similarly, studies targeting GLI1/2 expression or function in tumor cells in vitro or in mouse models of cancer have shown remarkable anti-tumor efficacy and concluded to a pathogenic role for the HH pathway, although most studies targeted its main downstream effectors, not the pathway itself." (PMID 32879407, 2020). "Therefore, we next analyzed whether EGF-mediated GLI1 suppression plays a role in modulation of tumor cell motility." (PMID 31867038, 2019). "Whereas the pictilisib-mediated Hhip upregulation can be explained by epigenetic events (please see Results section), the different effects on Gli1 expression in the in vitro vs. the in vivo situation could be due to e.g. drug pharmacokinetics or the tumor microenvironment." (PMID 30319965, 2018). "Similarly, tumours with an activating mutation in the HH pathway downstream of SMO, such as SUFU loss, or tumours that develop resistance to SMO inhibitors, may be responsive to GANT61 or similar inhibitors that target GLI1." (PMID 30068568, 2018).
tumor (continued). "The expression levels of aPKC-ι and GLI1 were significantly associated with advanced TNM stage (χ2 = 19.965, 15.458, respectively; P < 0.001), lymph node metastasis (χ2 = 13.125, 15.044, respectively; P < 0.001), and poor tumor differentiation (χ2 = 29.154, 15.273, respectively; P < 0.001) in GBC." (PMID 30389910, 2018). "Thus, mRNA expression data from human primary PCa samples indicate that the level of HH signaling (GLI1 expression) correlates with the proportion of stromal cells in a tumor, and IHH is increased more than the other HH ligands in tumors compared with normal prostate." (PMID 27935821, 2017). "Furthermore, given the correlation between high DHH and GLI1 expression and higher stromal content of human PCa samples, we hypothesized that increasing stromal HH signaling would decrease tumor progression by maintaining or increasing SM." (PMID 27935821, 2017). "Interestingly, SMARCA4 (also known as BRG1) is a transcriptional regulator that can control the activity of Sonic hedgehog and GliA and their downstream targets, providing a driving force for tumor proliferation by activating mitogenic genes such as GLI1, CCND1 and MYC." (PMID 29137349, 2017). "As a whole, these data may suggest the possibility that the ablation of Tis21, by altering the expression of important Shh marker genes such Pdgfd and Gli1, may increase the penetrance of the Shh-type tumor phenotype, but also the possibility of a shift of the Shh phenotype toward the group 3 MB." (PMID 27965576, 2016). "Moreover, RNAi-mediated GLI1 knockdown suppressed tumor formation and tumor sphere formation." (PMID 28105432, 2016). "However, as some CRC cell lines are dependent on GLI1 (refs 36, 40), it is possible that downstream Hh signalling might play a role in a tumour cell subpopulation." (PMID 27492255, 2016). "Furthermore, GLI1 has also been shown to have a potential role in tumor recurrence." (PMID 26633513, 2015). "Immunohistochemical staining of mice tumors revealed that Sonic hedgehog and nuclear Gli-1 expression transiently increased following docetaxel treatment, reached peak expression at day 8, and subsequently decreased to almost pre-treatment levels following regrowth of the tumor." (PMID 28203638, 2015). "Even though, many questions remain concerning how aberrant activation of GLI1 influences cell cycle checkpoints and DNA repair, there are few reports that clearly indicate potential mechanisms that GLI1 could control in order to protect tumor cells from oncogenic stress and chemotherapy." (PMID 26633513, 2015). "Whether the Hh/Gli1 pathway is involved in Cul4A-mediated EMT in tumour cells is unknown." (PMID 26218750, 2015). "Histologically these induced tumours contain poorly differentiated cells with abnormal nuclear morphologies, and in the case of Gli1-induced epidermal growths, the molecular phenotype suggests that these tadpole tumours may be equivalent of human basal cell carcinomas." (PMID 25704511, 2015). "As the GLI family of proteins are the final mediators of Hh signaling, their expression, especially that of GLI1, is deemed to be the best reflection of the net effect of Hh activation, thus, survival studies on GLI may indicate the potential involvement of Hh in tumor pathogenesis." (PMID 25103784, 2014). "Finally, during the early stages of carcinogenesis, the Shh reporter (i.e. the mCherry reporter linked to Gli1 responsive element) showed no Shh signaling until 30 dpf with a very slight increase at 2 mpf in tumor stroma." (PMID 24878567, 2014). "Interestingly, that work suggested that γ-secretase-mediated Notch inhibition may lead to a rise in Gli1 levels which may produce alterations in Hh signalling that in turn may promote tumour survival by Hh overactivation." (PMID 22550422, 2012).
tumor (continued). "In addition to these important discoveries, gene expression profiling studies have identified a number of novel wild-type GLI1 and tGLI1 target genes, linking wild-type GLI1 to tumor progression and therapeutic resistance, and tGLI1 to tumor invasion and migration." (PMID 21119888, 2010). "Therefore a functional involvement of GLI1 activity in human tumour development but also within cellular processes and maintenance of normal adult tissues might be concluded." (PMID 19706168, 2009). "With lower abundance (median IRS = 6) GLI1 was also expressed in the nucleus of normal breast cells, and therefore we suggest a general involvement of GLI1 in transcriptional regulatory processes that are not only important within tumour development but also in normal breast cells." (PMID 19706168, 2009). "The tumor site demonstrated a weak inverse correlation with NUPR1 promoter methylation (r = −0.12) and weak positive correlations with GLI1 (r = 0.22) and NDRG2 (r = 0.19) promoter methylation." (PMID 41596413, 2026). "The tumor suppressor RUNX3 can bind with GLI1 and promote its ubiquitination, thus resulting in an inversely expression of RUNX3 and GLI1." (PMID 41346572, 2025). "Emerging research depicts that the PI3K-AKT-mTOR signaling pathway regulates GLI1 expression independently of SMO in numerous cancers, promoting tumor development and progression 42-44." (PMID 39744485, 2025). "The activation of GLI1, 1 of 3 isoforms, is often considered a readout of Hh pathway activation, regulating genes such as MYCN, CYCLIN D, and BCL2 to control tumor progression." (PMID 40785845, 2025). "Conversely, MAML1 upregulation enhances Notch1 and Gli1 expression, driving accelerated TNBC tumor growth and faster multiorgan metastasis in vivo." (PMID 41272291, 2025). "The NOD‐SCID mice were transplanted with wild‐type (WT) PLC5 cells, GLI1 KO or CCL20 KO PLC5 cells, and the tumour growth was monitored over time." (PMID 40913253, 2025). "Subsequent cluster analysis based on mRNA expression indicated effective differentiation between tumor and normal tissues along the PC1 axis depending on their respective GLI1 and NLRP3 levels." (PMID 39744485, 2025). "It has been shown that Shh ligands have been identified in approximately 60% of HCC tumour tissues, and high expressions of PTCH‐1 and GLI1 mRNA have also been detected in HCC tissues." (PMID 40913253, 2025). "An analysis of 50 BTC cases found overexpression of GLI1 and PTCH1 in 50% and 30% of cases, respectively, with SHH pathway overactivation detected in 50% of tumor cells." (PMID 41465387, 2025). "In pancreatic cancer, Gli1 improves the drug‐efflux ability mediated by ABCG2, leading to gemcitabine resistance in tumour cells." (PMID 40665579, 2025). "In vivo, miR‐217 overexpression suppressed tumor growth, downregulated DNMT1 and GLI1, and increased apoptosis." (PMID 40909350, 2025). "The effect of GLI1 and CCL20 on tumour growth and monocyte infiltration was evaluated using a xenograft mouse model." (PMID 40913253, 2025). "However, since CSF1, a known target of the Hh pathway, can induce F4/80 expression in macrophages, we cannot exclude the possibility that the reduction in F4/80‐positive cells observed in GLI1 KO PLC5 tumour may be partially due to downregulation of CSF1 expression." (PMID 40913253, 2025). "The Hh pathway, through effectors such as GLI1, drives cellular proliferation and metastasis, while the HIPPO pathway acts as a tumor suppressor by regulating YAP/TAZ phosphorylation to inhibit their nuclear localization and oncogenic activity." (PMID 39846248, 2025). "Within the Pax6+ clusters 0–9, based on marker gene expression and cell cycle phase, clusters 3, 4, 8 were proliferative (Ki67+) and enriched for the GCP markers Gli1, Atoh1 and Barhl1, indicating highly proliferative GCP-like tumor cells." (PMID 40766638, 2025). "IHC analysis of ES patient tumor samples confirmed high levels of SMO and GLI1, which correlated with high C1GALT1 expression." (PMID 39894896, 2025).